HLA-DRA (major histocompatibility complex, class II, DR alpha)
Diseases named in the same sentence as HLA-DRA in open-access papers (continued):
Sharing a sentence is not in itself a finding about the gene and the disease.
Sepsis (continued). "In all patients mRNA expression of HLA-DRA was decreased by approximately 70% compared to controls (P<0.01) and was lowest in patients with sepsis or septic shock (P<0.01)." (PMID 28771573, 2017). "Corresponding to the FACS data, median mRNA levels of HLA-DRA were significantly decreased in sepsis patients compared to controls, which has been referenced to PPIB (P<0.001)." (PMID 28771573, 2017). "In a recently published prospective trial in 60 sepsis patients the group compared FACS data with mRNA expression data for HLA-DRA." (PMID 28771573, 2017). "Further, the HLA-DR MFI correlated strongly with HLA-DRA gene expression in sepsis patients (rho = 0.9, P<0.001)." (PMID 28771573, 2017). "In particular levels were lowest in group B compared to patients in group A: patients with post-surgical inflammation presented a 1.5-fold higher HLA-DRA expression compared to sepsis patients (P<0.05)." (PMID 28771573, 2017). "In this study we have shown that monitoring of HLA-DRA expression in whole blood using qRT-PCR is reliable for the detection of rapid dynamic changes in expression during bacteraemic sepsis." (PMID 27144640, 2016). "Our results showed that HLA-DRA measured by quantitative Real-Time PCR (qRT-PCR) correlated well with mHLA-DR in whole blood during Days 1–2 of sepsis." (PMID 27144640, 2016). "This implies that highly dynamic changes in gene expression in sepsis over time are detectable at the mRNA level (HLA-DRA) as well as in the surface expression of mHLA-DR." (PMID 27144640, 2016). "The transactivator of HLA-DRA gene transcription, a Class II transactivator (CIITA), was also found to be downregulated, and it is possible that HLA-DRA is under transcriptional control in sepsis." (PMID 27144640, 2016). "In this prospective study we evaluated dynamic changes in mHLA-DR expression during sepsis in relation to changes in HLA-DRA gene expression and Class II transactivator (CIITA), measured by quantitative Real-Time Polymerase Chain Reaction (qRT-PCR)." (PMID 27144640, 2016). "Our results also revealed dynamic HLA-DRA expression patterns during the course of sepsis that reflected those of mHLA-DR measured by FCM." (PMID 27144640, 2016). "• The mRNA levels of HLA-DRA and the monocyte surface expression of HLA-DR correlate highly in the early sepsis phase." (PMID 24093602, 2013). "In patients with sepsis (n = 59), blood samples were collected simultaneously for HLA-DR monitoring by qRT-PCR (transcripts of HLA-DRA and CIITA) and flow cytometry." (PMID 24093602, 2013). "The high correlation between mRNA levels of HLA-DRA and surface expression of HLA-DR and similarity in displaying variations according to sepsis severity and Gram-staining results indicates a possible consistency between the two methods." (PMID 24093602, 2013). "Furthermore, the dynamic changes in HLA-DRA gene expression and helper T cell subsets in patients with sepsis are indicative of immunosuppression." (PMID 37575977, 2023). "LASSO regression analysis identified C-reactive protein (CRP) and HLA-DRA mRNA as being repeatedly associated with sepsis, and no model was found to perform better than CRP alone in this setting (ROC-AUC 0.76 (0.68–0.84))." (PMID 34945111, 2021). "Using the SEPSIS-3 criteria, the PCT/HLA-DRA ratio also yielded better results than PCT to differentiate sepsis (n = 87 patients) from non sepsis patients (n = 53 patients): PCT [0.82 (0.75–0.90), 0.038]; PCT/HLA-DRA ratio [0.87 (0.81–0.93), 0.031] [AUROC (CI95%), p] (p = 0.004 in the Delong Test)." (PMID 30097607, 2018). "Next, we analyzed mRNA expression levels of HLA-DRA in controls and sepsis patients." (PMID 28771573, 2017). "Nevertheless, in order to be useful as biomarkers in sepsis, any method for measuring HLA-DRA and CIITA, expressed as a ratio to a reference gene, in this case peptidylpropylisomerase gene (PPIB), should be validated regarding its robustness during the course of sepsis." (PMID 27144640, 2016).
Sepsis (continued). "In summary, we have shown that monitoring of HLA-DRA at gene expression level using qRT-PCR was robust and showed dynamic changes over time in sepsis similar to the current gold standard of mHLA-DR monitoring by flow cytometry, but with a lesser degree of overlapping between severity groups." (PMID 27144640, 2016). "In pairwise testing of the differences between blood donors and septic patients at each time point, all biomarkers showed downregulated values until day 14 in the “severe sepsis/septic shock” group, although HLA-DRA and CIITA showed a greater magnitude of downregulation." (PMID 27144640, 2016). "In non-severe sepsis caused by Gram-positive bacteria (n = 21), HLA-DRA and mHLA-DR expression was significantly lower compared with healthy controls (P = 0.006 and P <0.0001, respectively)." (PMID 24093602, 2013). "The mRNA expression level of HLA-DRA monitored by qRT-PCR correlates highly with surface expression of HLA-DR and appears to be a promising future biomarker for evaluation of immunosuppression in sepsis." (PMID 24093602, 2013). "The mRNA expression level of HLA-DRA monitored by qRT-PCR correlates highly with surface expression of HLA-DR and appears to be a possible future biomarker for evaluation of immunosuppression in sepsis." (PMID 24093602, 2013). "In addition, we monitored by qRT-PCR the expression of five genes described in the literature to be involved in the ET refractory state or sepsis-induced immunosuppression (HLA-DRA, CIITA, IRAK-M, ABIN-3, and LY64)." (PMID 22027436, 2011). "Notably, miR-608 targets several inflammation-related transcripts as well as the histocompatibility antigen HLA-DRA, which is a biomarker for immunosuppression in sepsis, predictive of survival, and a surrogate marker for GM-CSF experimental therapy of sepsis." (PMID 29922126, 2018). "Moreover, mRNA HLA-DRA expression levels could differentiate between post-surgery and sepsis or septic shock patients." (PMID 28771573, 2017). "Similar to T cells and NK cells in sepsis, both naïve and switched resting B cell populations display significant decreases in the expression of several MHC-class II genes, including HLA-DRA, HLA-DRB1, HLA-DMA and HLA-DPA1." (PMID 41208955, 2025). "A six-gene panel including EOMES, LTF, CSF1R, HLA-DRA, IRF8 and MPEG1 was discovered and validated with a high accuracy both in sepsis subjects and sepsis-induced ARDS subjects." (PMID 37443002, 2023). "Four genes of them were differential expressed among sepsis-alone group, sepsis-induced ARDS group and controls, which were CSF1R, HLA-DRA, IRF8 and MPEG1." (PMID 37443002, 2023). "As an important finding, these interactions were confirmed for pairs of CTCF-sites and promoter regions of genes, which also displayed sepsis-induced alterations in our study (CM1 and HLA-DRA, CM2 and HLA-DRB1, CM9 and HLA-DPA1 and CM9 and HLA-DB1)." (PMID 33939725, 2021). "Some selected genes were significantly higher expressed in sepsis as compared with MBC samples (CD24, CD177, MMP8, and TLR5), and in MBC compared with sepsis (HLA-DRA, CSF1R, and AGAP6/9)." (PMID 32958605, 2020). "In the multivariate analysis, the ratio showed a superior ability to predict sepsis compared to that of PCT (OR [CI 95%], p): PCT/HLA-DRA: 7.66 [1.82–32.29], 0.006; PCT: 4.21 [1.15–15.43] 0.030." (PMID 30097607, 2018). "Multivariate analysis was confirmed using a new surgical cohort with 74 sepsis patients and 21 controls: PCT/HLA-DRA: 34.86 [1.22–995.08], 0.038; PCT: 5.52 [0.40–75.78], 0.201." (PMID 30097607, 2018). "According to our results, dynamic variations in HLA-DRA and CIITA gene expression can be reliably detected during the course of sepsis." (PMID 27144640, 2016). "The median values and interquartile ranges (IQR) of mHLA-DR, HLA-DRA and CIITA at each sampling according to sepsis severity at hospital admission." (PMID 27144640, 2016).
Sepsis (continued). "Consequently, we conclude that monitoring HLA-DRA by qRT-PCR allows detection of dynamic changes in the immune state in sepsis, and this technique may be used in future studies aiming to identify high-risk patients who might benefit from immunostimulation therapy." (PMID 27144640, 2016). "The aims of this study were to investigate if qRT-PCR measurement of HLA-DRA and CIITA was robust in terms of reproducibility, and if the changes in gene expression reflected shifts in mHLA-DR during the course of sepsis." (PMID 27144640, 2016). "Notably, HLA-DRA, IL1B, and CD86 were prominently elevated in Microglia 2 from sepsis patients, while P2RY12 and TREM2 were reduced, further supporting a pro-inflammatory shift." (PMID 41030458, 2025). "Additionally, five hub immune-related genes (CD3E, HLA-DRA, IL2RB, ITK and LAT) were identified from the protein–protein interaction network, and sepsis patients with higher expression of hub genes had a better prognosis." (PMID 38166628, 2024). "Additional experiments revealed that the observed elevation in CTCF expression, CTCF binding at CM1, CM2, CM3 and CM9 as well as the reduced expression of adjacent classical HLA genes HLA-DRA, HLA-DRB1, HLA-DPA1 and HLA-DPB1 persisted in all patients with postoperative sepsis." (PMID 33939725, 2021). "In the derivation cohort, AUROC analysis for differentiating survivors from non survivors in the group of patients with sepsis showed the following results: [AUROC, (confidence interval 95%), p]: PCT [0.78, (0.68–0.77) <0.001]; PCT/HLA-DRA [0.79, (0.70–0.89), <0.001]." (PMID 30097607, 2018). "The objective of this study was to evaluate the accuracy of the combination between PCT levels in plasma and expression levels in blood of HLA-DRA to differentiate surgical patients with sepsis from those with no sepsis." (PMID 30097607, 2018). "Here we evaluated the combination of procalcitonin (PCT) with gene expression levels of HLA-DRA to detect sepsis in a cohort of 154 surgical patients (101 with sepsis and 53 with no infection)." (PMID 30097607, 2018). "Moreover, HLA-DRA measured by qRT-PCR discriminated better between high and low SOFA scores among the patients with severe sepsis and septic shock, than did mHLA-DR measured by flow cytometry." (PMID 27144640, 2016). "We conclude that qRT-PCR measurement of HLA-DRA expression is robust, and that this method appears to be preferable to FCM in identifying patients with severe sepsis that may benefit from immunostimulation." (PMID 27144640, 2016). "In particular, mHLA-DR discriminated between severe and non-severe sepsis in the early stage of sepsis only, while HLA-DRA- and CIITA-mRNA levels measured by qRT-PCR, showed prolonged divergence between our severity groups." (PMID 27144640, 2016). "There were significant differences in both mHLA-DR and HLA-DRA expression between the two groups of non-severe (n = 48) and severe (n = 11) sepsis/septic shock (mHLA-DR P = 0.029, HLA-DRA P = 0.009)." (PMID 24093602, 2013). "Even more importantly, the observed reduction in classical HLA-DRA, HLA-DRB1, HLA-DPA1 and HLA-DPB1 transcription as well as the decline in monocyte HLA-DR surface expression persisted in all patients with postoperative sepsis despite a recovery of CIITA transcription levels during the study period." (PMID 33939725, 2021). "This feature of HLA-DRA could make PCR assessment a favourable biomarker method to distinguish between severe and non-severe disease during the course of sepsis." (PMID 27144640, 2016). "Furthermore, HLA-DRA and mHLA-DR recovery slopes in patients with non-severe sepsis differed from those in patients with severe sepsis, shown by mixed model for repeated measurements (p<0.05)." (PMID 27144640, 2016). "Based on the statistical interaction tests, we evaluated whether or not the means of mHLA-DR, and HLA-DRA showed different recovery patterns over time and whether patterns differed between”non-severe sepsis” and “severe sepsis/septic shock”." (PMID 27144640, 2016).
Sepsis (continued). "Indeed, patients who do not survive sepsis have decreased HLA-DRA, -DMA, -DMB, and CD74 mRNA expression in whole blood and reduced HLA-DR expression on the cell surface of circulating monocytes." (PMID 19903332, 2009). "The AUROC of PCT for differentiating between the group of sepsis patients and the group of surgical controls with no infection was compared against that obtained for the PCT/HLA-DRA ratio in the derivation cohort." (PMID 30097607, 2018). "HLA-DRA and CIITA decreased to a greater extent in the “severe sepsis/septic shock” group and to a lesser extent in the “non-severe sepsis” group, than did mHLA-DR measured by flow cytometry." (PMID 27144640, 2016). "The mean difference of mHLA-DR, HLA-DRA and CIITA between severity groups (severe sepsis and septic shock/non-severe sepsis), calculated on logarithmic scale, expressed as ratios and presented at each time point." (PMID 27144640, 2016). "Our study demonstrates that the PCT/HLA-DRA ratio outperforms PCT independently of the presence or absence of septic shock in the sepsis patients, although it yielded the largest differences in distinguishing sepsis patients with no septic shock from the uninfected surgical controls." (PMID 30097607, 2018).
melanoma (20 papers, 2008 to 2025). A malignant, usually aggressive tumor composed of atypical, neoplastic melanocytes. "Similarly, genes related to melanoma invasion were downregulated in SIRT2-deficient melanoma cell lines (e.g., HLA-DRA, IL-6, CD74, and HLA-DRB1 in the SSW30 clone, Dataset S1; PTPRZ1, FST, and NRCAM in the SSM15 clone, Dataset S2)." (PMID 31091806, 2019). "HLA-DRa also exhibited heterogenous expression in melanoma lesions and cell lines, with IFNγ being a strong inducer of HLA class II expression." (PMID 36389735, 2022). "Although melanoma cells acquire HLA-DRA expression during tumor development, the prognostic value of this expression has not been clarified." (PMID 18211678, 2008). "The other two genes from the Met library (PLP-1 and HLA-DRA) did not exhibit expression pattern clearly associated to any specific stage of the melanoma progression in this study (bottom)." (PMID 18211678, 2008). "A six-gene IFN-γ signature (including IDO1, CXCL10, CXCL9, HLA-DRA, STAT1, and IFNG) was identified in a melanoma cohort of the KEYNOTE-001 study to predict response to pembrolizumab." (PMID 35222540, 2022). "As for anti-PD-1 blockade, the IFN-γ gene signature (IDO1, CXCL10, CXCL9, HLA-DRA, STAT1, and IFNG) predicts the response to anti-PD-1 therapy in multiple tumors, including melanoma." (PMID 34439264, 2021). "MHC-II molecules, particularly HLA-DRA, are critical for antigen presentation to CD4+ T cell and required for antiPD-1/PD-L1 activity in melanoma; agents that induce MHC-II positivity can be combined with PD-1/PD-L1-targeted therapy to improve response rates." (PMID 33747255, 2021). "In the KEYNOTE-001 study, six gene signatures of INFG-related genes (IDO1, HLA-DRA, STAT1, CXCL9, IFNG and CXCL10) were previously developed in melanoma patients." (PMID 32107458, 2020). "Using the Oncomine database and cBioPortal for public microarray data of cutaneous melanoma, we selected three datasets composed of melanoma tumor samples to analyze the genes co-expressed with HLA class II genes, specifically HLA-DPA1 and HLA-DRA." (PMID 31212865, 2019). "To confirm this correlation, we analyzed RNA-seq data from seven different melanoma-derived cell lines and found that CIITA transcript levels correlated strongly with HLA-DRA and HLA-DRB levels across this panel of melanoma lines." (PMID 28647344, 2017). "To assess the significance of MHC class II expression in human melanocytic neoplasia, we mined human melanoma Cancer Genome Atlas data comparing expression of CIITA, HLA-DRA, and HLA-DRB with patient survival." (PMID 28647344, 2017). "Even though expression of SV40 T antigen suppressed induction of HLA-DRA and HLA-DRB, it is well documented that MHC class II expression is typically found in 50–60% of freshly isolated melanomas." (PMID 28647344, 2017). "Meanwhile, HLA-DRA, INHBA, DKK1, CTGF, PMP22, FLRT3 and NRCAM genes, upregulated in G10, were described as overexpressed in invasive melanomas." (PMID 27206673, 2016). "Other research found that class II molecules (HLA-DPA1, HLA-DPB1, HLA-DQA1, HLA-DRA, HLA-DRB1, HLA-DRB5) are important biomarkers in the occurrence and progression of melanoma tumors, and their expression levels are closely related to prognosis and immune infiltration." (PMID 39969704, 2025). "Therefore, the melanoma cell lines analyzed here express differential levels of HLA-DRA but without showing correlation to any particular phase of the tumor development." (PMID 18211678, 2008). "The cell surface protein expression patterns of these markers in our melanoma panel did not precisely reflect their transcript expression patterns in the human SKCM dataset of TCGA (n = 472), although both protein and transcript expression of PD-L2 (PDCD1LG2) and HLA-DR (HLA-DRA) were correlated." (PMID 29977240, 2018).
breast carcinoma (14 papers, 2012 to 2025). "HLA-DRA was overexpressed in hepatocellular carcinoma, colorectal cancer, and cervical cancer, but was decreased in breast cancer." (PMID 39346909, 2024). "HLA-DRA exhibited upregulation in colon cancer and hepatocellular carcinoma while demonstrating downregulation in breast cancer." (PMID 38877387, 2024). "Overexpression of HLA-DRA was reported in hepatocellular cancer, colorectal cancer, and cervical cancer, while it was decreased in breast cancer." (PMID 35794593, 2022). "Another study reports that downregulation of EZH2 results in significant increases in CIITA and HLA-DRA expression as well as increased cell surface expression of MHC II in breast cancer." (PMID 29132376, 2017). "HLA-DRA has been studied in cervical cancer, low-grade gliomas, renal clear cell carcinoma, pediatric adrenocortical tumors, non-small cell lung cancer, and breast cancer." (PMID 40565031, 2025). "Research has demonstrated that HLA-DRA serves as a significant prognostic factor for breast cancer." (PMID 39471412, 2024). "It was observed that a reduction in EZH435 expression in the human breast cancer cell line MDA-MB-231 significantly increased HLA-DRA mRNA expression, even without IFN-γ stimulation." (PMID 38795164, 2024).